KRAS (KRas proto-oncogene, GTPase)
Diseases named in the same sentence as KRAS in open-access papers (continued):
Sharing a sentence is not in itself a finding about the gene and the disease.
lung cancer (continued). "KRAS mutation was frequently found in our LM patients, and evidence suggests KRAS-mutated tumors are commonly associated with lung cancer cachexia." (PMID 36774484, 2023). "Combined inhibition of KRAS or its proximal effectors along with feedback pathways is a potential efficacious strategy to treat KRAS-mutated lung cancer." (PMID 37816716, 2023). "KRAS mutant lung cancer is frequently co-mutated with the tumor suppressors LKB1 and KEAP1, which have both been shown to drive immune evasion." (PMID 37581538, 2023). "In 2021, the FDA granted accelerated approval to Sotorasib, the first KRAS-inhibitor for patients with KRAS p.G12C-mutated lung cancer." (PMID 35796778, 2023). "KRAS mutations in isogenic lung cancer cell lines have differentially methylated CpGs and an enrichment for genes involved in development and differentiation." (PMID 38068961, 2023). "Experiments in a larger panel of cell lines spanning all KRAS mutations found in lung cancer will aid to resolve the overall involvement of KRAS in treatment response." (PMID 37816716, 2023). "The most frequent allelic variant of KRAS mutant lung cancer is the smoking related G12C which became the focus of the development of mutant-specific irreversible KRAS inhibitors." (PMID 38239281, 2023). "KRAS mutation in lung cancer has three predominant forms: the most frequent is G12C (∼40%) followed by ∼20–20%, G12D and G12V, respectively." (PMID 38239281, 2023). "Our recent study of human lung cancer indicates that KRAS mutation occurred only in ≤10% of the patients while microRNA alteration was constantly present in all the cancer-bearing patients." (PMID 37511536, 2023). "In this study, we elucidate an association between several measures of neighborhood socioeconomic disadvantage and somatic KRAS mutations in lung cancer patients." (PMID 36383274, 2023). "The implementation of combinatorial approaches involving MEK1/2 or KRASG12C inhibitors in the context of KRAS-mutated lung cancers focuses fundamentally on targeting KRAS proximal activators or effectors." (PMID 37816716, 2023). "Worse cancer-specific and overall survival have been associated to KRAS mutation and copy number gain in lung cancer." (PMID 37007070, 2023). "In lung cancer driven by oncogenic KRAS mutation, abrogation of AMPK led to substantial impairment of tumor growth, revealing the role of AMPK to promote lysosome expansion and autophagy." (PMID 36685038, 2023). "High levels of IL17A in KRAS mutant mice promoted IL-6 and G-CSF secretion by binding to IL-17 receptor A on the surface of lung cancer cells, leading to increased invasion of tumor-associated neutrophils." (PMID 37670322, 2023). "Although KRAS G12C is the most common KRAS mutation in lung cancer, G12V and G12D driver mutations predominate in pancreatic cancers." (PMID 37655310, 2023). "The mutation of RBM10 co-exists with the known lung cancer target genes KRAS, EGFR, and PIK3CA, among others." (PMID 37509501, 2023). "The high frequency of KRAS mutation in lung cancer is often associated with increased invasiveness, poor prognosis, and drug resistance." (PMID 37941550, 2023).
lung cancer (continued). "The oncogene KRAS has been heavily studied as a frequently mutated gene in various cancers, including colorectal, pancreatic, and lung cancers." (PMID 36752207, 2023). "Manoalide, a natural inhibitor of PLA2, has been identified as a potential EGFR-TKI sensitizer for KRAS-mutated and osimertinib-resistant lung cancer organoid by inhibiting the KRAS-ERK signaling pathway." (PMID 37941550, 2023). "KRAS mutation was more likely to be harbored in patients with current/ex-smoking history, International Association for the Study of Lung Cancer (IASLC) grade 3, or accompanied lymphatic or vascular invasion." (PMID 36918771, 2023). "The function of CRAF in PDAC markedly differs from its role in KRAS mutant lung cancer, and the underlying mechanism for the disparity remains elusive." (PMID 38111008, 2023). "We next assessed the impact of UHRF1 loss on the in vivo growth of human KRAS-driven lung adenocarcinoma cells using a competitive growth assay in a xenograft model of lung cancer." (PMID 37407562, 2023). "All cell lines were isolated from C57BL/6 mice and express the mRNA encoding the EML4-ALK variant 1 fusion gene compared to KRAS-mutant murine LLC lung cancer cells." (PMID 36739466, 2023). "KRAS co-mutations have been studied to determine their effects on prognosis in lung cancer patients." (PMID 38067288, 2023). "LKB1 is an important human tumor suppressor gene, and in non−small cell lung cancer (NSCLC) patients LKB1 mutations or genomic loss frequently co−occur with KRAS alterations." (PMID 36979667, 2023). "From 28,120 registered patients with lung cancer, 1185 were selected with a KRAS mutation, of which 494 had a KRAS G12C mutation." (PMID 37674812, 2023). "Deltarasin has been shown to induce apoptosis and autophagy in KRAS-mutated lung cancer cell line experiments as well as decreased tumor growth in vivo." (PMID 37569406, 2023). "KRAS mutation is the most frequent type of genetic mutation in non‐small cell lung cancer (NSCLC), especially in lung adenocarcinoma." (PMID 37226642, 2023). "It is becoming increasingly apparent that complex KRAS downstream interactions and co-mutations also influence tumour signalling in lung cancer." (PMID 38067288, 2023). "The major focus will be on those clinical trials performed specifically in 3 tumor entities, i.e., pancreatic, CRC and lung cancers with frequent mutations in the KRAS gene." (PMID 36313934, 2023). "Together, these results suggested that KRAS mutations endowed lung cancer cells with an antiphagocytic capacity during tumor progression." (PMID 36413402, 2023). "KRAS mutations frequently occur in exon 2 at codon 12 and these alterations give rise to lung cancer development." (PMID 37041291, 2023). "We did not observe statistically relevant associations between GR expression and other common lung cancer driver mutations, including KRAS and EGFR." (PMID 37035141, 2023). "Both EGFR and KRAS are important driver mutations in lung cancer, however, they were mutually exclusive between G1 and G2 groups." (PMID 37388220, 2023). "While activating mutations in the KRAS oncogene occur in nearly one-third of non–small cell lung cancers (NSCLCs), effective therapeutic options for these malignancies remain limited." (PMID 37384411, 2023). "For example, the KRAS mutation G12C is associated with an increased risk of lung cancer, and G12D is associated with an increased risk of pancreatic cancer." (PMID 37174676, 2023). "Accordingly, AhR has been reported to suppress some lung cancers, including those with KRAS-driver mutations characteristic of PAH-induced genotoxicity and smoking." (PMID 37696458, 2023). "In patients with lung carcinoma, the KRAS G12C actionable mutation (AF: 24.55%, 51.46%, 21.32%, and 27.18%) was present in 4 (18.18%) patients, and the treatment options were sotorasib and bevacizumab plus chemotherapy (Tier IA)." (PMID 37371673, 2023).
lung cancer (continued). "FOXA3 and SPDEF induce MUC5AC and MUC5B, while HNF4A induces MUC3 in human lung cancer cells harboring a KRAS mutation." (PMID 36860703, 2022). "AKT1 has been identified as a candidate driver gene in adenocarcinoma and has been identified as an important regulator of invasion and metastasis of lung cancer cells having KRAS or EGFR mutations." (PMID 35932303, 2022). "The most common lung cancer oncogenic alteration mutation is in the KRAS, being related to smoking and poor prognosis in NSCLC." (PMID 35599008, 2022). "KRAS mutations are more commonly associated with lung cancers diagnosed in smokers and are reported to be positive in about 40% of cases." (PMID 35805276, 2022). "In this study, we analyzed the clinical, histological, immunohistochemical, and molecular profiles of 202 KRAS G12C-mutated LUADs to advance current knowledge of this subset of lung cancers." (PMID 35205778, 2022). "For instance, among KRAS mutation predominant cancers, KRAS-G12C mutations mainly occur in lung cancer (45%), whereas KRAS-G12D mutations are related to more than 50% of pancreatic ductal adenocarcinoma cases." (PMID 36430338, 2022). "Intra-tumor heterogeneity and different treatment responses are a current challenge in developing targeted therapies in patients with lung cancer and KRAS mutation." (PMID 36012655, 2022). "Second, we performed a similar sequencing-based assay in A549 cells engineered to express either wild-type or mutant KRAS, or other lung cancer-associated variants." (PMID 36522653, 2022). "Kirsten rat sarcoma viral oncogene homolog (KRAS) is the most common oncogenic driver in solid tumors including lung cancer and was associated with a worse prognosis and resistance to chemotherapy and anti-epidermal growth factor receptor (EGFR) treatment." (PMID 36230855, 2022). "Mutant KRAS (KM) is associated with poor prognosis in lung cancer and reported to promote lipid metabolism." (PMID 35882862, 2022). "Strategies for lung cancer patients with KRAS mutations and EGFR-TKI resistance are limited, and it is imperative to develop new EGFR-TKI sensitizers and combination strategies to overcome resistance to EGFR-TKIs." (PMID 36712673, 2022). "Our study determines the drug-addicted phenotype in lung cancer is associated with KRAS amplification and demonstrates that toxic acquired genetic changes can develop de novo in the background of MAPK suppression with MEK inhibitors." (PMID 36418460, 2022). "KRAS mutations are the drivers of various cancers, including non–small cell lung cancer, colon cancer, and pancreatic cancer." (PMID 35014625, 2022). "While KRAS G12C mutations are more prevalent in lung cancer, KRAS G12D mutation is the most common in PDAC as well as CRC." (PMID 36531078, 2022). "In a recent randomized phase- III study, however, lung cancer patients with KRAS mutation received either erlotinib or abemaciclib monotherapy." (PMID 35814226, 2022). "In this study, aged patients with lung cancer showed some specific gene alterations, such as a relative high proportion KRAS codon 61 in the KRAS mutated patients, and the various mechanism of EGFR TKIs resistance." (PMID 35031014, 2022). "We and other groups have previously established that the KRAS mutation drives lung cancer, pancreatic cancer, and colon cancer." (PMID 35563733, 2022). "The two isoforms coexist in cells, and although KRAS-4B is the most common, both can cause lung cancer in mice." (PMID 35406400, 2022).
lung cancer (continued). "MA also suppresses the KRAS-ERK pathway through ROS and promotes the sensitivity of KRAS-mutated lung cancer cells and organoids to osimertinib." (PMID 36712673, 2022). "We have found in current work that almost half of the KRAS mutation positive lung cancer patients express low level of ZNF24." (PMID 36457047, 2022). "In this study, we analyzed the clinical and molecular features of 87 KRAS-mutated lung cancer patients treated with ICIs at the City of Hope." (PMID 36230855, 2022). "Some evidence suggests that additional KRAS mutations can co-occur with KRAS G12C, and has been observed in colorectal, gastric and lung cancer patients." (PMID 35177674, 2022). "There have been an increasing number of studies on KRASG12C, the most common KRAS mutation in lung cancer individuals." (PMID 35631410, 2022). "In conclusion, the Lung Cancer Compact Panel was effective in detecting KRAS G12D, and its use in analyzing gene mutations is recommended even when the tumor cell content of the specimen is low." (PMID 35545933, 2022). "KRAS transversions (G > T) in patients with lung cancer is thought to be caused by exposure to polycyclic aromatic hydrocarbons, such as benzopyrene in cigarettes." (PMID 36348317, 2022). "In summary, we showed a higher cytotoxicity effect of allitinib in a representative panel of lung cancer, and the sensibility was associated with KRAS mutant status." (PMID 35887120, 2022). "STK11 and KEAP1 comutations have been associated with worse outcomes in patients with KRAS-mutant lung cancer treated with an ICI." (PMID 36426286, 2022). "KRAS mutations are prevalent in pancreatic cancer (90%), lung cancer (20–30%), and endometrial cancer (18%)." (PMID 35307764, 2022). "Despite some encouraging data on G12C and G13C inhibitors in lung cancer, G12D and G12V mutations are the most prevalent KRAS mutations in CRC associated with worse overall survival." (PMID 35307764, 2022). "In this study, we analyzed the clinical and molecular characteristics of 87 lung cancer patients with mutated KRAS who had received monotherapy ICIs to identify the associations with the clinical outcomes of responses and overall survival (OS)." (PMID 36230855, 2022). "Central and West Africa are the regions with the lowest incidence rates of lung cancer for both sexes (0.8%) worldwide, while in North Africa, the KRAS mutations is observed in 6–9% of patients." (PMID 36077640, 2022). "This targeting approach has been also supported by other studies that take advantage of a mutation in the KRAS oncogene, G12S, to specifically inhibit the proliferation of G12S-bearing lung cancer A549 cells." (PMID 36139356, 2022). "More importantly, KRAS is the most frequent oncogene in non-small cell lung cancer and the lung cancers activated by KRAS mutation have serious outcomes in both early-stage and advanced metastatic settings." (PMID 35991047, 2022). "In conclusion, only tobacco smoking is strictly related to the occurrence of KRAS mutations in lung cancer patients." (PMID 36077640, 2022). "Upregulation of SAM leads to increased DNA methylation in lung cancer cells with KRAS/LKB1 co-mutations." (PMID 36074553, 2022). "Taken together, these results showed that MA significantly reduced the viability and proliferation of KRAS-mutated lung cancer cells and organoids, indicating that MA is a potential suppressor of KRAS-mutated lung cancer." (PMID 36712673, 2022).
lung cancer (continued). "Our findings will have immediate clinical value, as KRAS mutations and PD-L1 expression are routinely assessed in most patients diagnosed with lung cancer." (PMID 35565194, 2022). "The results showed that the combination treatment of MA and osimertinib decreased the proliferation of KRAS-mutated lung cancer cells of A549 and H157 compared to the osimertinib treatment group at a low dose (1 μM)." (PMID 36712673, 2022). "We found that a significant portion of KRAS mutation positive lung cancer patients express low level of ZNF24 (designated Zno/K* patients)." (PMID 36457047, 2022). "In the present study, we compared the in vitro efficacy of EGFR inhibitors (afatinib and allitinib) and conducted a comprehensive analysis of the molecular mechanisms triggered by KRAS mutations in a panel of lung cancer cell lines." (PMID 35887120, 2022). "To establish the in vitro drug screening system, we constructed primary KRAS-mutated lung cancer organoids from a mouse model of KrasG12D-driven lung cancer." (PMID 36712673, 2022). "In the Phase II clinical trial of KRAS-mutated lung cancer patients, 50% of them exhibited specific antigen-antibody reactivity." (PMID 36118526, 2022). "Although EGFR and KRAS mutations typically occur in a mutually exclusive fashion in lung cancer; anecdotal reports show evidence of co-occurrence of KRAS and EGFR mutations in lung cancer patients." (PMID 35251972, 2022). "Mutational cooperation between LKB1 loss and KRAS activation leads to induction of the serine–glycine–one-carbon pathway in lung cancer cells which results in enhanced S-adenosyl methionine (SAM) synthesis as a critical substrate for DNA methylation." (PMID 36074553, 2022). "Mutations in KRAS are common among the three deadliest cancers: pancreatic, colorectal, and lung cancers." (PMID 35631410, 2022). "Researchers determined that smoking history is essential in the regulation of KRAS mutation in lung cancer." (PMID 35409064, 2022). "Although they rarely occur in lung cancer, KRAS mutations combined with EGFR mutations or ALK rearrangement predict poorer response to tyrosine kinase inhibitors (TKIs)." (PMID 36077640, 2022). "We report here some of the major and specific knowledge in the field, mainly considering the signaling pathways induced in lung cancer cells by the KRAS mutation." (PMID 35406400, 2022). "We analyzed lung cancer cohorts with KRAS mutations (GSE31210) and found that higher hub gene levels (BUB1, BUB1B, NCAPG, CDC20, CDK1, KIF11) were significantly associated with worse OS in lung cancer patients with KRAS mutations." (PMID 36176446, 2022). "As such, KRAS has been shown to be associated with disorders including lung cancers and cholangiocarcinoma." (PMID 35086473, 2022). "There are certainly rational arguments to make for this combination, with KRAS-mutant lung cancer generally being associated with a smoking history and therefore high tumor mutation burden, one of the positive predictors for response to ICB." (PMID 35857848, 2022). "It has been reported that the prevalence of KRAS mutation in lung cancer is significantly lower in Asian populations than in Western populations." (PMID 36076922, 2022). "Combined inhibition of mTOR by rapamycin and of MEK by trametinib achieved tumor suppression in lung cancer models carrying KRAS mutations." (PMID 36048281, 2022). "Based on the data in COSMIC, missense mutations of KRAS frequently occur in pancreatic, colorectal and lung cancers." (PMID 36330448, 2022). "KRAS mutations, with codons 12 and 13 mutations being the most frequent, are oncogenic drivers in lung cancer." (PMID 35031014, 2022).